NLRP3 (NLR family pyrin domain containing 3)
Diseases named in the same sentence as NLRP3 in open-access papers (continued):
Sharing a sentence is not in itself a finding about the gene and the disease.
breast cancer (continued). "In particular, the increased expression of NLRP3 in human Breast Cancer Associated Fibroblasts (CAFs) is a precursor to cancer progression and metastasis through secretion of IL-1β which stimulates angiogenesis, immune evasion, epithelial-mesenchymal transition (EMT), and stemness." (PMID 41560727, 2025). "NLRP3 activation is linked to the infiltration of MDSCs and TAMs in breast cancer." (PMID 41291696, 2025). "In addition to the inflammatory responses, NLRP3 also has been shown to be associated with the progression of various human cancers, including colorectal and breast cancers as well as acute myeloid leukemia." (PMID 39144184, 2024). "The inflammasome NLRP3 is associated with breast cancer, but there are few specific reviews." (PMID 37300757, 2023). "In addition, PEI 25 kD administration can cause NLRP3 inflammasome activation in breast cancer tissues and induce high levels of oxidative stress." (PMID 37300757, 2023). "Furthermore, NLRP3 inflammasome activation in NLRP3 TAMs correlates with neutrophil infiltration in the tumors and is associated with poor outcome in breast cancer patients." (PMID 36711732, 2023). "As expected from the immunofluorescence studies, breast cancer brain metastases were associated with the upregulation of Nlrp3 and Il1b gene expression in the hemisphere comprising the metastatic cells compared to the contralateral side, serving as an internal control." (PMID 37749707, 2023). "Breast Cancer development has been linked to the NLRP3 inflammasome." (PMID 37300757, 2023). "The contribution of inflammasome activation in the generation of a tumor-supporting microenvironment is underpinned by the finding that NLRP3 activation in breast cancer-associated fibroblasts modify the expression of adhesion molecules, thus promoting metastatic spread." (PMID 34070682, 2021). "Thus, the dual function of a TAK1 inhibitors to cause cancer cell death while simultaneously activating NLRP3 makes them a potential powerful anticancer agent for breast cancer." (PMID 33840390, 2021). "Moreover, inflammatory reactions caused by the NLRP3 inflammasome in fibroblasts leads to breast cancer progression and metastasis to both the liver and lung tissue." (PMID 34457117, 2021). "This is exemplified by cancer-associated fibroblast (CAF) expression of NLRP3, which contributes to tumorigenesis and metastasis in several breast cancer models, including the syngeneic PyMT-derived mammary tumor cell lines, AT3 and Met-1, and the 4T1 mammary carcinoma cell line." (PMID 34638239, 2021). "In this study, we evaluated how isolated NETs modulate the NLRP3 inflammasome in a human breast cancer model." (PMID 41828456, 2026). "Previous reports have shown that increased FOSL1 activates the IL‐6‐STAT3 signaling pathway either directly or through NLRP3‐mediated inflammation in breast cancer and psoriasis." (PMID 41556041, 2026). "Our findings revealed novel cross-organ pathogenic communication between breast cancer and the heart through the exosomal miR-216a-5p-mediated ITCH/TXNIP/NLRP3 pathway, which drives cardiomyocyte pyroptosis." (PMID 40360476, 2025). "Scientific studies conducted in recent years have highlighted the impact of NLRP3 inflammasome signaling on the breast cancer mechanism." (PMID 39940603, 2025). "Liu and their team conducted a study to examine the expression and significance of GSDMD-N and NLRP3 in breast cancer." (PMID 39744516, 2025). "High NLRP3 expression correlated with worse patient survival, highlighting potential prognostic relevance in breast cancer." (PMID 41148809, 2025). "In cancer models, such as breast cancer, miR-223-3p inhibits NLRP3 activation, suppresses tumor progression, and enhances anti-tumor immune responses." (PMID 41560727, 2025). "Even though the results of in vitro studies are valuable, advanced in vivo studies are also needed to better understand the mechanisms of the NLRP3 inflammasome and pyroptosis in the breast cancer context." (PMID 39940603, 2025).
breast cancer (continued). "The scientific literature suggests the interconnection between NLRP3 inflammasome signaling and breast cancer, especially TNBC progression." (PMID 39940603, 2025). "In breast cancer, CAFs-driven NLRP3 and IL-1β drive tumor growth and metastasis by orchestrating an immune-suppressive microenvironment." (PMID 41291696, 2025). "In breast cancer, the activation of NLRP3 stimulates the secretion of IL-1β, which promotes EMT and facilitates metastasis." (PMID 39858497, 2025). "They analyzed 90 breast cancer tissue samples to understand the association between pyroptosis effectors GSDMD-N and NLRP3." (PMID 39744516, 2025). "High expression of Nlrp3 is correlated with poor survival in patients with breast cancer, likely through its role in inducing Epithelial‒Mesenchymal Transition (EMT), as well as in patients with colorectal cancer." (PMID 40195474, 2025). "Immunocytochemical staining of murine mammary carcinoma tissue demonstrated that SNRPE silencing increased NLRP3 expression as well as the formation of the characteristic ASC specks." (PMID 40386046, 2025). "Modulating NLRP3 inflammasome activity has been proposed as a potential therapeutic strategy for breast cancer treatment." (PMID 39769450, 2024). "The Dinarello group reported that activation of NLRP3 dictated a response to anti-PD-1 therapy in a breast cancer model and suggested that NLRP3 is a key driver of immune suppression." (PMID 39796680, 2024). "So, we conclude that CAV1 in BC-derived sEVs promote neutrophil recruitment through the TLR4-NF-κB-IL-6/CCL2 axis and neutrophil N2-type polarization through the TLR4/NF-κB/NLRP3 pathway, thus promoting the lung metastasis of breast cancer." (PMID 39494337, 2024). "Recent studies have shown the significance of NLRP3 inflammasome and its involvement in breast cancer progression and metastasis, indicating its potential as an innovative therapeutic target." (PMID 39769450, 2024). "In breast cancer, DAMPs can trigger the activation of the NLRP3 inflammasome and induce pyroptosis in CAFs through the NLRP3/caspase-1/GSDMD pathway." (PMID 38649701, 2024). "Gene expression analysis suggested the potential of NLRP3 inflammasome modulation to counterbalance breast cancer cells growth by activating the immunogenic cell death (pyroptosis) and inhibiting the activity of pro-inflammatory cytokines, IL-1β and IL-18." (PMID 39433537, 2024). "Further, NLRP3 inflammasome inactivation driven by microRNA (miR)-223-3p has been shown to reduce tumor growth and increase anticancer immunity in breast cancer." (PMID 39769450, 2024). "The genetic locus of miR-233 plays a role in promoting cancer cell growth and angiogenesis, and the elevated expression of NLRP3 after miR-233 depletion in breast cancer cells suggests other possibilities for activating NLRP3 against tumors." (PMID 38001342, 2024). "Our previous study showed that VX765, an agent that blocks NLRP3-dependent cytokine release by suppressing caspase-1, increased cell proliferation in epithelial cancer cells, such as prostate, lung, and breast cancers." (PMID 38543085, 2024). "Although it has been reported that several types of amyloids can activate the NLRP3 inflammasome, including SAA and amyloid-β, the role of SAA signaling in NLRP3 activation in breast cancer is limited." (PMID 39336082, 2024). "Previous research has shown that genetic ablation of NLRP3 can restore caspase-7 activity in breast cancer cells, indicating a possible connection between inflammasome activation and apoptosis modulation in cancer." (PMID 39336082, 2024).
breast cancer (continued). "In conclusion, inflammation emerges as a dominant force in promoting breast cancer occurrence, and NLRP3 inhibitory drugs, studied extensively to impede inflammasome activation, provide a new direction and hope for breast cancer treatment." (PMID 38317229, 2024). "This aberrant ROS accumulation subsequently activates the NLRP3 inflammasome and promotes breast cancer bone metastasis." (PMID 39472438, 2024). "The NLRP3 inflammasome-mediated inflammatory response plays a significant role in breast cancer progression and metastasis." (PMID 39769450, 2024). "Among these, inhibitors targeting the NLRP3 inflammasome by blocking the IL-1 signaling pathway prove effective in breast cancer treatment." (PMID 38317229, 2024). "Here, we show the novel role of SAA1/2 in modulating the NLRP3 inflammasome, apoptosis, and necrosis in breast cancer." (PMID 39336082, 2024). "The NLRP3 inflammasome has been shown to promote breast cancer growth and metastasis by inducing IL-1β secretion, which stimulates angiogenesis, immune evasion, epithelial-mesenchymal transition (EMT), and stemness." (PMID 37715239, 2023). "Compared with normal breast tissue, the expression of Nlrp3, caspase-1 and IL-1β genes in the NLRP3 inflammatory pathway was significantly upregulated in mouse and human mammary tumor stroma." (PMID 37020871, 2023). "Other studies found that activating the NLRP3 inflammasome promoted breast cancer metastasis to liver and lung tissues." (PMID 37715239, 2023). "In breast cancer cells, the expression levels of NLRP3 and IL-1β are significantly higher compared to normal tissues, contributing to the occurrence of pyroptosis in the tumor microenvironment." (PMID 37542283, 2023). "Quercetin, the active ingredient from the Protracted Anti-Aid Detoxification Formula, has antitumor activity in a variety of cancers and inhibits caspase-1-mediated scorching by downregulating PYD, ASC, and NLRP3 in breast cancer." (PMID 37542283, 2023). "For example, in one report NLRP3 inflammasome activation was shown to promote autocrine IL-1β secretion in breast cancer, in turn inducing the epithelial-mesenchymal transition and metastatic progression." (PMID 37885032, 2023). "Further research is needed for breast cancer and NLRP3 relation despite the many treatments available." (PMID 37300757, 2023). "In the TCGA breast cancer dataset, NLRP3 had a positive correlation with survival in all molecular subtypes." (PMID 37715239, 2023). "Clinical data have shown a positive correlation between the activation of inflammasomes, especially NLRP3, and metastasis, late clinical stages, and poor survival rate in breast cancer and lung cancer patients." (PMID 36932407, 2023). "A number of studies have suggested that NLRP3 activation plays a role in the development of breast cancer." (PMID 37300757, 2023). "Several previous studies had investigated the location and expression characteristics of NLRP3 inflammasome in breast cancer tissues." (PMID 38031068, 2023). "Western blot analysis demonstrated that knockdown of ZNF‐148 increased the expression levels of pyroptosis‐associated biomarkers (NLRP3, ASC, IL‐1β, and IL‐18) in breast cancer cells, which was reversed by cotreating cells with NAC and ALA." (PMID 37909239, 2023). "Further studies are still needed to explore the close relationship between NLRP3 inflammasome and the post-operative long-term prognosis of breast cancer patients." (PMID 38031068, 2023). "Treatment with a caspase-1 inhibitor and NLRP3 gene silencing inhibited leptin-induced proliferation of breast cancer cells by promoting cell cycle progression and suppressing cell death." (PMID 37715239, 2023). "This review article discusses NLRP3 and its role in breast cancer, including its potential as a therapeutic target." (PMID 37300757, 2023).
breast cancer (continued). "It has been broadly reported that the increased expression of NLRP3 inflammasome in breast CAFs and TAMs, the two major cells in the stroma of breast tumor, contribute to tumor progression and metastasis of breast cancer patients." (PMID 38031068, 2023). "In the immune-stromal cells, all the five NLRP3 inflammasome pathway-related proteins were significantly elevated in breast cancer tissues compared with adjacent normal tissues (P < 0.05)." (PMID 38031068, 2023). "And the potential strategies of using NLRP3 inflammasome to target breast cancer, such as NLRP3-based nanoparticle technology and gene target therapy, are reviewed." (PMID 37300757, 2023). "When referring to breast cancer, basic studies have made some important hints indicating the NLRP3 inflammasome pathway as a possible therapeutic target for the prevention and treatment of breast cancer." (PMID 38031068, 2023). "Through searching for the NCBI GEO dataset, the expression of NLRP3, PYCARD, CASP1, and IL-1β genes in the tumor-associated stroma of breast cancer patients were found to be increased with the pathological stage when compared with normal breast stroma." (PMID 38031068, 2023). "A previous study on breast cancer demonstrated that silibinin treatment impairs mitochondrial dynamics, decreases ROS levels, and prevents NLRP3 inflammasome activation in MDA-MB-231 cells." (PMID 37731666, 2023). "In conclusion, our study reveals that the activation of NLRP3 inflammasome pathways in immune-stromal and tumor parenchymal cells were not isotropic and the main functions are somewhat different in breast cancer patients." (PMID 38031068, 2023). "Fibroblast-derived IL-1β is secreted through NLRP3 inflammasomes, which are activated by various DAMPs including necrotic fluid from breast cancer cells." (PMID 36932407, 2023). "For example, cisplatin has been demonstrated to be involved in NLRP3/caspase-1/GSDMD pyroptosis pathway in breast cancer cells." (PMID 36932407, 2023). "Another study highlighted that NLRP3-induced pyroptosis and IL-1β secretion create an immune suppressive environment in breast cancer." (PMID 37629059, 2023). "Increased expression of NLRP3 protein was mainly detected in the nuclei of astrocytes treated with breast cancer cell-conditioned media." (PMID 37749707, 2023). "In breast cancer, the NLRP3 inflammasome pathway is closely related to tumor proliferation, angiogenesis, and invasiveness." (PMID 38031068, 2023). "NLRP3 and IL-1 expression in TAMs, on the other hand, was associated with survival, lymph node invasion, and metastasis in patients with HER2 + breast cancer." (PMID 37715239, 2023). "Noteworthy, Raut and coworkers demonstrated that leptin, one of the major adipokines produced in obese conditions and related to tumor growth, is able to activate NLRP3 inflammasomes in MCF-7 breast cancer cells." (PMID 37819510, 2023). "It has been reported in a review that NLRP3, IL-1β, and IL-18 motivate the development of tumors in lung cancer, melanoma, and breast cancer." (PMID 36119049, 2022). "Both pyroptosis-related inflammasomes including NLRP1, NLRP3, NLRC4, AIM2, and the following inflammatory cytokines IL-1β and IL-18 are associated with the immune system in breast cancer." (PMID 36119049, 2022). "GBP-5 promotes NLRP3 inflammasome assembly, but it is unclear how that influences breast cancer prognosis." (PMID 35681772, 2022). "The translocation of MDSCs and TAMs into the TME was triggered by NLRP3-mediated pyroptosis and the liberation of IL-1 at primary and metastatic locations, which induced the growth and metastasis of human breast cancer." (PMID 36119049, 2022). "In this study, we showed that IL-1β production in breast cancers is driven by NLRP3 activation in myeloid cells at disease baseline." (PMID 35631400, 2022). "Given the inhibition of NLRP3 inflammasome in blocking breast cancer progression, various agents inhibiting inflammasomes can be utilized for therapeutic strategies." (PMID 36119049, 2022).
breast cancer (continued). "For example, activation of NLRP3 can promote tumor progression and metastasis in breast cancer, and the NLRP3 inflammasome can induce cell proliferation, invasion, and tumor development in GC cells." (PMID 36541912, 2022). "MiR-223, a miRNA with tumor suppressing capacity, was shown to block translation of NLRP3 mRNA and suppress the breast cancer cell growth." (PMID 36517518, 2022). "In the current study, we demonstrated that metastatic breast cancer cells induce activation of NLRP3 in myeloid cells, ultimately resulting in an immunosuppressive TME." (PMID 35631400, 2022). "As a central target in the classical pathway, NLRP3 has been found to be aberrantly expressed in a variety of malignancies, such as ovarian cancer and breast cancer." (PMID 36467503, 2022). "Cisplatin induced anti-breast cancer effects at least partly by activating MEG3/NLRP3/caspase-1/GSDMD pathway." (PMID 36936274, 2022). "A recent study demonstrated that Chinese propolis (25, 50 & 100 μg/ml) treatment inhibits cell proliferation by targeting glycolysis enzymes and proinflammatory cytokines including TNF-α, IL-6, and NLRP3 in the breast cancer cells." (PMID 35754701, 2022). "The aim of the study: In this study, NLRP3 inflammasome activation in breast cancers cell lines, MCF-7 (ER-α+) and, MDA-MB-231(ER-α−), was analyzed." (PMID 36517518, 2022). "Another study also demonstrated that NLRP3 pyroptosis caused IL-1β maturation and the resulting CCL5, CXCL12, CCL2, and CXCL5 expression, which enhanced metastasis of breast cancer by recruiting MDSC and M2 macrophages." (PMID 36119049, 2022). "In the context of breast cancer, it has been demonstrated that IL-1β and NLRP3 were overexpressed in the breast tumor microenvironment concomitantly to the accumulation of MDSCs and TAMs." (PMID 33840390, 2021). "Here, we sought to verify the specificity of the Caspase protein involved in DOX‐induced pyroptosis on breast cancer cells by evaluating the protein expression of NLRP3 and interleukin‐1β in both MDA‐MB‐231 and T47D cell lines." (PMID 34369076, 2021). "The same authors recently determined that inflammasome components can be regulated by the P2Y2R activation and are involved in tumor progression evidencing that NLRP3 and caspase-1 mRNA levels were upregulated in radiotherapy-resistant breast cancer cells." (PMID 33840390, 2021). "While the IL1 pathway mainly activated by NLRP3 inflammasomes contributes to the progression and metastasis of breast cancer." (PMID 33821998, 2021). "Treatment with a pharmacological inhibitor of caspase-1 and gene silencing of NLRP3 prevented leptin—induced growth of breast cancer cells via promotion of cell cycle progression and suppression of cell apoptosis." (PMID 33840390, 2021). "Although further studies are needed, these data depict a clear protumoral role for NLRP3 in mammary cancer." (PMID 34064909, 2021). "The utilization of therapeutic strategies against the NLRP3 inflammasome to block breast cancer progression depends on the different molecular subtypes and patient heterogeneity." (PMID 33840390, 2021). "Increased NLRP3 expression in TAMs is correlated with lymph node invasion and metastasis in breast cancer patients." (PMID 34771482, 2021). "In agreement, NLRP3 knock-out mice, orthotopically transplanted with breast cancer cells, display less pulmonary metastases." (PMID 34070682, 2021). "Inhibitors of the IL-1 signaling pathway that block the IL-1α or IL-1β receptor are the most efficient examples of therapies used in breast cancer targeting the NLRP3 inflammasome." (PMID 33840390, 2021). "On the other hand, the protumor effect of the NLRP3 inflammasome in breast cancer progression has been described as resulting in infiltrating myeloid-derived suppressor cells and tumor-associated macrophages to the tumor site." (PMID 34502191, 2021).